INS (insulin)
Diseases named in the same sentence as INS in open-access papers (continued):
Sharing a sentence is not in itself a finding about the gene and the disease.
Obesity (continued). "However, the physiological and molecular mechanisms of HIIT intervention in obesity, like energy metabolism, mitochondrial function, inflammatory reaction, insulin sensitivity, and other regulatory factors, require further study." (PMID 37608837, 2023). "Moreover, poor sleep pattern was associated with disrupted insulin homeostasis (elevated FBG) and obesity (elevated WC and BMI)." (PMID 37033270, 2023). "However, ongoing research on therapies for obesity-associated NAFLD includes diet and lifestyle modification for weight loss, the use of the supplements and insulin sensitizers, and surgery." (PMID 38140297, 2023). "As obesity progresses, adipocyte hyperplasia and hypertrophy increase, such that excessive lipid accumulation in adipose tissue increases serum lipid levels and flux in the skeletal muscle, promoting insulin resistance and muscle atrophy." (PMID 37681878, 2023). "Subtle but neat differences in the circulating lipids, as well as in insulin sensitivity could be established, which opens the possibility to personalize the treatment according to the patients categorization into such obesity subtypes." (PMID 38174068, 2023). "Additionally, studies have shown that Romboutsia is negatively correlated with fasting glucose, insulin, and high-density lipoprotein cholesterol; and positively correlated with indicators of obesity." (PMID 36985331, 2023). "Present results expand on the body of evidence indicating that sucralose consumption during pregnancy can predispose the offspring to low-grade systemic inflammation, a condition concurring with weight gain and altered insulin secretion in patients with obesity and metabolic dysfunction." (PMID 36979631, 2023). "Thus, HFD treatment induced paternal obesity and impaired glucose homeostasis and insulin-mediated glucose uptake." (PMID 37887423, 2023). "To overcome this limitation, we assume that the insulin sensitivity function also depends on the obesity-related factor X (i.e. assuming C(I, X) decreases as X increases), accounting for the elevated insulin resistance driven by increased adiposity and free fatty acids." (PMID 36848379, 2023). "Studies have demonstrated the role of hypercaloric diets in the development of experimental models of obesity due to changes in body composition, such as increased body weight (BW) and fat deposits, changes in glycemic and lipid profiles, insulin resistance, and hypertriglyceridemia." (PMID 37032431, 2023). "In this study, we prepared a macromolecular polysaccharide, SjC, from S. japonica and the in vivo experiment demonstrated that oral treatment with SjC could efficiently prevent HFD-induced obesity, insulin, and glucose metabolism disorders." (PMID 36766192, 2023). "With regard to obesity and fatty liver, we postulate that insulin clearance increases first to compensate for the high concentration of circulating insulin; then, it declines when insulin levels become too high, and obesity comorbidities and altered glucose homeostasis manifest." (PMID 37834412, 2023). "However, when individuals engage in long-duration training at moderate intensity (at 40–50% of maximum power), this leads to the oxidation of body fat and thus decreases insulin concentration, which makes it tolerable for people suffering from obesity." (PMID 37508677, 2023). "Furthermore, BATSP1 reduces high-fat diet (HFD)-induced obesity and improves glucose metabolism and insulin sensitivity upon mild cold exposure." (PMID 38010450, 2023). "The relatively low percentage of children with abnormal glucose and insulin fasting levels may be attributed to the young age of the patients and the moderate degree of obesity." (PMID 37892696, 2023). "Whether clinical outcomes predicted using non-insulin-based IR indices are also affected by the obesity paradox remains unknown." (PMID 37255931, 2023).
Obesity (continued). "Consistent with this, results from a longitudinal study in humans that evaluated changes in endocrine factors (i.e., ghrelin, insulin, and leptin) in obesity assessed before and after bariatric surgery, reported a decrease in ghrelin, insulin, and leptin after the intervention." (PMID 37261609, 2023). "Indeed, the A allele has been associated with an improvement of anthropometric measures, lipid profile, and insulin sensitivity following a hypocaloric diet in patients with obesity." (PMID 36986146, 2023). "Four key factors may explain the connection between obesity and thyroid cancer: thyroid hormones, Insulin resistance, adipokines, and inflammation." (PMID 37940857, 2023). "It is known that exercise has beneficial effects on glucose homeostasis, and can enhance insulin sensitivity, and may therefore have a direct role in preventing laminitis through physiological effects and/or by reducing obesity." (PMID 37328910, 2023). "In addition, obesity-induced hypermetabolism stimulates osteoblasts directly by increasing insulin signaling." (PMID 37705039, 2023). "Between Tanner stages 1–3, there is an increase in fasting glucose, insulin and acute insulin response and an associated reduction in insulin sensitivity independent of sex or obesity status." (PMID 37441710, 2023). "The results from our study demonstrate that the heterogeneity in the effects of marked weight loss on muscle and hepatic insulin sensitivity in people with obesity is determined by baseline insulin action, and reaches a ceiling when “normal” insulin action is achieved." (PMID 37159276, 2023). "In addition, obesity leads to metabolic changes, such as increased insulin secretion and growth factor, which can also play a role in the early tooth eruption." (PMID 37933401, 2023). "This study investigated whether CF consumption improved whole-body insulin-mediated glucose uptake (‘M’) in females with overweight/obesity, using a randomized, double-blinded, placebo-controlled, parallel-group design." (PMID 36771271, 2023). "The results highlighted that subjects with severe obesity and insulin resistance were characterized by a decrease in the abundance of Bacillota and, in particular, of the Ruminococcaceae family, when compared to obese subjects with normal insulin sensitivity." (PMID 37049562, 2023). "The underlying pathogenesis of hypertension in TS is multifactorial with impaired vagal tone, congenital cardiovascular and renal anomalies, higher cortisol levels, impaired insulin resistance and the metabolic syndrome in the context of obesity all considered to be potential contributing factors." (PMID 36471031, 2023). "In addition to body mass index (BMI) and leptin as measures of obesity and adiposity, we metabolically phenotyped women by their fasting glucose, C-peptide and insulin sensitivity (ISHOMA index)." (PMID 37029207, 2023). "Finally, obesity-induced hyperglycemia increases insulin signaling, glycolytic pathway activity, oxidative stress, and DNA alterations." (PMID 36670988, 2023). "Both genes have known functions that could modulate obesity, lipid metabolism, insulin secretion, and/or glucose homeostasis." (PMID 36717164, 2023). "In our study, liver dysfunction caused by fibrosis was more severe in the infected obesity group, explaining a significant decrease in insulin levels compared to the noninfected obesity group." (PMID 37296126, 2023). "At hormonal levels, a stepwise increase in insulin and leptin and a reduction in ghrelin, with possible consequences on the imbalance of the gustatory signaling and food reward, has been found in subjects affected by OW and stages I–II obesity." (PMID 38313840, 2023). "However, when put on a high-fat diet (HFD), F4MKO mice appeared to be protected from diet-induced obesity, and showed improved glucose tolerance and increased insulin sensitivity." (PMID 37770480, 2023). "Higher insulin concentrations were observed in the obesity group." (PMID 37892696, 2023).
Obesity (continued). "Many studies have clearly shown that among children and adolescents with overweight and obesity, particularly those with central fat distribution, levels of insulin may be increased and dyslipidemia may occur." (PMID 37761412, 2023). "Compared with obesity, which is detrimental to health, decreased insulin sensitivity is beneficial for fetal growth and energy requirements during lactation, but in sows, excessive decreased insulin sensitivity during the perinatal period leads to decreased feeding during lactation." (PMID 36676993, 2023). "Consumption of breast milk may protect against the development of obesity because of lower protein intake, lower insulin release, or different future dietary preferences." (PMID 36879421, 2023). "In addition to increased RV afterload due to obesity-related LVDD, circulating cytokines, growth hormones, adipokines (leptin, Ang II, insulin, and aldosterone), BP, and nocturnal hypoxemia contribute to obesity-related RV remodeling." (PMID 37176781, 2023). "It is documented that vaspin may have positive effects on glucose and insulin metabolism, lipid profile, appetite control, and arteriosclerosis, thus counteracting obesity, IR, and inflammation." (PMID 36979443, 2023). "At hormonal levels—in line with the current literature—patients affected by OW and stages I–II of obesity demonstrated a progressive increase in leptin and insulin and a reduction in ghrelin, possibly impacting the imbalance of the taste signaling and food reward." (PMID 36904115, 2023). "Impaired insulin homeostasis is common in obesity and metabolic disorders." (PMID 37828911, 2023). "In addition to its anti-inflammatory action, adiponectin relieves hyperglycemia and improves insulin sensitivity in humans and rodents with obesity by acting on skeletal muscle and the liver." (PMID 36834930, 2023). "Given that insulin use is associated with weight gain, managing weight may be challenging for those with T2DM and obesity." (PMID 37456411, 2023). "As a result, reducing the number of macrophages in adipose tissue slows the onset of obesity and improves insulin sensitivity and glucose metabolism, indicating that macrophages in adipose tissue play crucial roles in the development of obesity and metabolic disorders." (PMID 37153549, 2023). "We measured the insulin signaling pathway in adipose tissue-derived exosome-treated AML12 cells to determine whether obesity would affect this pathway." (PMID 37229466, 2023). "Despite the fact that BC is well known to be associated with metabolic characteristics of T2D, including hyperglycemia, hyperinsulinemia, inflammation, oxidative stress, and obesity, randomized controlled trials show opposite results for metformin as an insulin sensitizer." (PMID 36849958, 2023). "Interestingly, compared with littermate controls, adipocyte-specific Sparc-KO mice (Adip-KO) were protected from HFD-induced obesity and displayed improved glucose tolerance and insulin-sensitivity." (PMID 37781916, 2023). "Dietary habits that elicit an increased insulin response may contribute to the development of obesity and fat storage." (PMID 37645243, 2023). "Cd exposure is believed to affect the incidence of obesity by acting on PPAR-γ, causing hyperplasia and hypertrophy of adipose tissues, disrupting endocrine homeostasis, altering appetite and satiety regulation and affecting insulin sensitivity." (PMID 37240215, 2023). "Indeed, systemic inflammation, resistance to insulin’s physiological actions, altered myocardial energetics and MVD are highly implicated in the pathogenesis of HFpEF in patients with obesity, T2D and metabolic syndrome." (PMID 37658327, 2023). "Obesity is known to promote breast cancer progression through leptin and insulin signaling." (PMID 36732635, 2023). "Indeed, decreased vitamin D is associated with MetS as a whole, and with some components, such as obesity, increased BMI, dyslipidemia, increased blood pressure, and altered insulin and glucose metabolism." (PMID 37047134, 2023).
Obesity (continued). "Therefore, we assume that our obesity-like in vitro conditions triggered neuronal dysfunction related to insulin signaling and synaptic formation and glial dysfunction related to phagocytosis and Chol uptake, leading to cognitive impairment." (PMID 37047207, 2023). "This implies that obesity could also impact the expression and activity of visfatin in the body, which could potentially affect insulin sensitivity and glucose metabolism." (PMID 38155161, 2023). "FA2H may be a factor involved in obesity-induced insulin resistance as FA2H downregulation through the micro-RNA miR-3075 led to enhanced insulin signaling." (PMID 36902339, 2023). "Furthermore, it has been shown that the administration of JWH-133 reduces body weight gain, relieves glucose tolerance, and enhances insulin sensitivity in mice models of obesity." (PMID 38139344, 2023). "Other Bacteroides species are also reported to prevent obesity and increase insulin sensitivity." (PMID 37242791, 2023). "However, although most obese patients show impaired insulin sensitivity, approximately 30% of obese patients are known as metabolically healthy obesity in clinical observations." (PMID 37884540, 2023). "Although no studies have directly investigated the relationship between Erysipelotrichaceae and inflammation, some studies have found that the absence of congenital immune receptor NLRP12 can make mice prone to obesity, decrease insulin sensitivity and increase adipose tissue inflammation." (PMID 37293204, 2023). "The application of ketogenic protocols in women with overweight or obesity and infertility is based on the possibility to reduce insulin levels, improving hormonal balance, restoring ovulatory cycles and improving oocyte and embryo quality, as well as pregnancy rates even in subjects undergoing IVF." (PMID 37405618, 2023). "Obesity significantly decreases life expectancy and increases the incidence of age‐related dysfunctions, including β‐cell dysregulation leading to inadequate insulin secretion." (PMID 37060190, 2023). "The exact mechanism by which obesity raises the risk of RCC is uncertain, but the accumulation of body fat directly affects insulin levels in the body, thereby elevating the probability of hypertension, both of which are strongly associated with the development of RCC." (PMID 37266130, 2023). "Adipokines are promising pharmacological treatment targets for obesity and metabolic disorders as they regulate appetite and satiety, energy expenditure, blood pressure, endothelial function, insulin sensitivity, adipogenesis, fat distribution and insulin secretion." (PMID 37576981, 2023). "Three weeks of combined treatment of resveratrol and rosiglitazone did not alter body weight changes in aKQ mice after obesity induction, but caused slightly worse insulin sensitivity and more favorable glucose tolerance in aKQ mice." (PMID 37408258, 2023). "Apart from obesity increasing insulin, IGF-1, leptin, IL-6, TNF-α and decreasing levels of adiponectin which activates the PI3K-AKT signalling pathway in CRC, high BMI inhibits methylation of PI3K-AKT signalling pathway genes, constitutively activating the pathway." (PMID 37233716, 2023). "AKT2 is a major AKT isoform expressed in insulin-sensitive tissues like liver, its liver-specific deletion inhibits hepatic TG accumulation, further supporting the importance of PI3K/AKT signaling activation in obesity-associated HCC." (PMID 37361533, 2023). "Increasing evidence suggests that an inability to adapt to metabolic stimuli, such as insulin signaling or fatty acid exposure, may lead to the decrease in muscle oxidative capacity characteristic of obesity." (PMID 37374197, 2023). "In addition, the postoperative GH response in persons with obesity undergoing bariatric surgery seems to be mainly modulated by insulin." (PMID 36959287, 2023).
Obesity (continued). "Overall, considering that obesity is usually accompanied by increased serum insulin levels, which are known to activate GSK3β, there is still a possibility that obesity can facilitate M2-like phenotype and thereby promote HCC progression in certain circumstances." (PMID 37266440, 2023). "Impaired insulin signaling in peripheral tissues, caused by HFD consumption that was even more pronounced in APP/PS1 mice, could lead to obesity and T2DM as a result of IR, as described in the study of Huang." (PMID 37686722, 2023). "Some studies pointed out that BAT was a target to prevent the development of obesity, as enhancing its thermogenic activity could increase insulin sensitivity and ameliorate lipid metabolism." (PMID 37892414, 2023). "Contrastingly, subjects using sulfonylurea or insulin or who had obesity at baseline were significantly less likely to continue treatment with dulaglutide (OR [95% CI]: 0.41 (0.20, 0.81), 0.26 (0.11, 0.58), and 0.33 (0.11, 0.91), respectively; with all p < 0.05)." (PMID 37305431, 2023). "The complexity of obesity is underscored by the multiple hypotheses proposed to pinpoint its seminal mechanisms, such as the “energy balance” hypothesis and the “carbohydrate–insulin” model." (PMID 38048365, 2023). "In this study, it was shown that the level of insulin could improve after (pre)treated rats with a variety of doses of garlic in male rats with obesity." (PMID 36644444, 2023). "In obesity, leptin and insulin levels are elevated due to increased fat mass and IR." (PMID 38136211, 2023). "Since circulating levels of fetuin-A are increased in obesity, metabolic syndrome, and T2D, and correlate to impaired insulin sensitivity and glucose intolerance, they represent a promising biomarker and might serve as a therapeutic target." (PMID 36769005, 2023). "However, this statement was contradicted by another study that showed the increased level of acetate was involved in increasing insulin and ghrelin leading to obesity." (PMID 37861729, 2023). "Nevertheless, the increased insulin clearance observed in HFD-SG mice was linked to higher hepatic IDE expression, thus, pointing to SG as a good strategy to counteract hyperinsulinemia in obesity pathology." (PMID 36675244, 2023). "While obesity, a leading risk of T2D, increases IL-33 production in both human and mouse islets, it also interferes with the IL-33-ILC2 axis and its ability to promote insulin secretion." (PMID 36967785, 2023). "The worsening in eGFR in case of overweight or obesity may be explained by worse metabolic parameters such as lipids and insulin sensitivity, which may impact kidney function." (PMID 36670673, 2023). "Obesity impairs brain function and synapse formation by impairing insulin signaling." (PMID 37047207, 2023). "The positive relationship between obesity and urologic cancers has been confirmed by several studies, and the mechanisms may be related to insulin resistance, abnormal IGF system, ectopic fat deposition, and microbiome alterations." (PMID 37764869, 2023). "This approach yielded four subgroups that had only some overlap with the five initial clusters regarding clinical, treatment-related and complication profiles: obesity- and age-related (68%), malnutrition-related (18%), body fat-related and insulin-resistant (8%), and ketosis-prone (6%)." (PMID 37402743, 2023). "This suggests that insulin sensitizers may provide an important future direction for the treatment of NAFLD in PCOS patients with obesity." (PMID 37720537, 2023). "This theory was followed by a series of studies on mice and cell cultures indicating that the downregulation of Toll-like receptor 2 (TLR2) and Toll-like receptor 4 (TLR4) in diet-induced obesity improves adipocyte differentiation and insulin sensitivity in mice." (PMID 37446161, 2023).